LINC00674 (long independently transcribed non-coding RNA 674)
Synonyms: CALA
Gene: Transcribed unprocessed pseudogene on chromosome 17 (68,101,908 to 68,114,527, forward strand). Ensembl gene ENSG00000237854.
Diseases named in the same sentence as LINC00674 in open-access papers:
LINC00674 is named in the same sentence as 10 diseases in open-access papers, as found by Europe PMC text mining. Sharing a sentence is not in itself a finding about the gene and the disease. The quoted sentences say what the papers report.
colon cancer (2 papers, 2015 to 2021). "Among these lincRNAs, LINC00674 has been reported to promote tumor progression in hepatocellular carcinoma, colon cancer, and glioblastoma, whereas the function of LINC00493 is largely unknown." (PMID 34148056, 2021).
tumor (3 papers, 2015 to 2022). "We found that LINC00674 expression was closely correlated to tumor size (P=0.004), venous infiltration (P=0.017), and TNM stage (P=0.014)." (PMID 36118523, 2022). "LINC00674 contributed to the malignant behaviors of tumor cells, possibly by activating the NADPH oxidase 1 (NOX1)/mTOR signaling pathway in HCC." (PMID 36118523, 2022). "RT-qPCR assay confirmed the lower levels of LINC00674 in tumor tissues collected from the LINC00674 knockdown group (P<0.05)." (PMID 36118523, 2022). "LINC00674 overexpression was closely related to large tumor, venous infiltration, advanced tumor stage and unfavorable prognosis of HCC patients." (PMID 36118523, 2022). "RAPA treatment remarkably abolished the tumor-promoting role of LINC00674 in HCC cells (P<0.05)." (PMID 36118523, 2022). "In addition, RT-qPCR analysis revealed that LINC00674 expression in HCC was dramatically higher compared to that in non-tumor tissues (P<0.05), which was consistent with the TCGA data from the GEPIA web server 22 (P<0.05)." (PMID 36118523, 2022). "Notably, NOX1 knockdown remarkably abolished the tumor-promoting role of LINC00674 in HCC cells (P<0.05)." (PMID 36118523, 2022). "Thus, we suggested that LINC00674 activated the mTOR signaling pathway and facilitated tumor progression by enhancing NOX1 expression in HCC cells." (PMID 36118523, 2022). "Moreover, the staining of Ki-67 and NOX1 in tumor tissues obtained from the LINC00674 knockdown group was significantly weaker than the control group (P<0.05)." (PMID 36118523, 2022). "Notably, NOX1 knockdown remarkably abolished the tumor-promoting role of LINC00674 in HCC cells." (PMID 36118523, 2022).
LINC00674 also shares sentences with these, for which no sentence is quoted: cancer (2 papers); hepatocellular carcinoma (2); acute myeloid leukemia (1); aspergillosis (1); glioblastoma (1); infection (1); infectious disease (1); kidney stone (1).